BCL7B (BAF chromatin remodeling complex subunit BCL7B)
Description:
Positive regulator of apoptosis. Plays a role in the Wnt signaling pathway, negatively regulating the expression of Wnt signaling components CTNNB1 and HMGA1. Involved in cell cycle progression, maintenance of the nuclear structure and stem cell differentiation. May play a role in lung tumor development or progression (By similarity).
Synonyms: SMARCJ2
Tractability: PROTAC: ubiquitination databases record sites on it.
Gene: Protein-coding gene on chromosome 7 (73,536,355 to 73,557,699, reverse strand). Ensembl gene ENSG00000106635.
Subcellular location (Human Protein Atlas): Nucleoplasm
Pathways (Reactome):
Chromatin organization: Formation of neuronal progenitor and neuronal BAF (npBAF and nBAF); Formation of the canonical BAF (cBAF) complex; Formation of the embryonic stem cell BAF (esBAF) complex; Formation of the non-canonical BAF (ncBAF) complex; Formation of the polybromo-BAF (pBAF) complex
Developmental Biology: Regulation of MITF-M-dependent genes involved in pigmentation
Gene expression (Transcription): Regulation of endogenous retroelements by Piwi-interacting RNAs (piRNAs)
Gene Ontology:
Molecular function: protein binding; actin binding
Biological process: chromatin remodeling; negative regulation of cell differentiation; positive regulation of cell population proliferation; positive regulation of double-strand break repair; positive regulation of stem cell population maintenance; regulation of G0 to G1 transition; regulation of G1/S transition of mitotic cell cycle; regulation of mitotic metaphase/anaphase transition; regulation of nucleotide-excision repair; regulation of transcription by RNA polymerase II
Cellular component: SWI/SNF complex; chromatin; GBAF complex; nucleoplasm
Genetic constraint (gnomAD): Loss-of-function variants: 11 observed, 20.99 expected, observed/expected ratio (o/e) 0.52, 90% interval 0.33 to 0.87. The upper end of that interval is the gene's LOEUF score, 0.87, which puts it in group 3 of 6, group 1 being the genes least tolerant of losing a copy. Missense variants: 209 observed, 235.09 expected, observed/expected ratio (o/e) 0.89, 90% interval 0.79 to 1. Synonymous variants: 109 observed, 100.33 expected, observed/expected ratio (o/e) 1.09, 90% interval 0.93 to 1.27.
Homologues: Orthologues: guinea pig BCL7B (98% identical), pig BCL7B (98% identical), mouse Bcl7b (96% identical), rat Bcl7b (96% identical), rabbit BCL7B (94% identical), dog TBL2 (87% identical), macaque BCL7B (86% identical), chimpanzee BCL7B (84% identical), tropical clawed frog bcl7b (66% identical), zebrafish bcl7ba (65% identical), zebrafish bcl7bb (62% identical), Drosophila melanogaster BCL7-like (31% identical), and 1 more. Paralogues in human: BCL7C (49% identical), BCL7A (47% identical).
Diseases named in the same sentence as BCL7B in open-access papers:
BCL7B is named in the same sentence as 54 diseases in open-access papers, as found by Europe PMC text mining. Sharing a sentence is not in itself a finding about the gene and the disease. The quoted sentences say what the papers report.
gastric cancer (3 papers, 2015 to 2024). A primary or metastatic malignant neoplasm involving the stomach. "To understand the mechanisms by which BCL7B is involved in cancer pathology, we generated BCL7B-deficient stomach cancer cell lines, and comprehensive gene expression profile of the control cells was compared to the profile of deficient cell lines by RNA-seq." (PMID 37648998, 2023). "In this study, we investigated the functional roles of the bcl-7 and BCL7B genes in the Wnt signaling pathway and apoptosis in C. elegans and in human gastric cancer cells, respectively." (PMID 25569233, 2015). "Knockdown of BCL7B in human gastric cancer cells were shown to suppress cell death." (PMID 39902046, 2024). "Furthermore, in KATOIII human gastric cancer cells, BCL7B knockdown induced nuclear enlargement, promoted the multinuclei phenotype and suppressed cell death." (PMID 25569233, 2015). "Furthermore, in KATOIII human gastric cancer cells, BCL7B knockdown induces nuclear enlargement, as observed in Caenorhabditis elegans, and promotes the multinucleated phenotype, both of which are reminiscent of malignant diseases." (PMID 25569233, 2015). "Additionally, similar to its role in C. elegans, human BCL7B functions as a negative regulator of Wnt signaling, presumably upstream of ß-catenin, and induces apoptosis in gastric cancer cells." (PMID 25569233, 2015). "In addition, it has been reported that in the bcl-7 mutant of Caenorhabditis elegans, the nuclei in stem cells, which are called seam cells in this organism, and the nuclei in the human stomach cancer cell line (the Kato III cell line) are enlarged when BCL7B expression is downregulated by siRNA." (PMID 37648998, 2023). "In addition, we also analyzed the function of the BCL7B gene in both pathways in KATOIII cells, a human gastric cancer cell line." (PMID 25569233, 2015).
glioma (3 papers, 2021 to 2023). A benign or malignant brain and spinal cord tumor that arises from glial cells (astrocytes, oligodendrocytes, ependymal cells). "Besides, the overall survival of glioma patients expressing high BCL7B was significantly worse than their counterparts expressing low BCL7B in CGGA and TCGA (HR = 2.706 and 3.560, respectively, all p < 0.05)." (PMID 34362400, 2021). "OS showed that BCL7B was significantly related to the prognosis of GBM (p = 0.014), glioma (GBMLGG, p < 0.001), KICH (p = 0.041), KIRC (p = 0.022), LGG (p = 0.001), OSCC (p = 0.035), sarcoma (SARC, p = 0.002), and uveal melanoma (UVM, p = 0.045)." (PMID 35910232, 2022). "Contrarily, BCL7B expression was mainly enriched in GBM and was elevated with an increase in glioma grade." (PMID 34362400, 2021). "Results from immunohistochemical (IHC) staining and public dataset validation demonstrated that BCL7B and BCL7C were highly expressed in glioma tissues compared to NBT." (PMID 34362400, 2021). "BCL7B and BCL7C were not independent risk factors for poor prognosis in all-gliomas patients in TCGA and CGGA datasets (respectively)." (PMID 34362400, 2021).
pancreatic cancer (3 papers, 2019 to 2022). "BCL7B was found as a predictor of poor prognosis of pancreatic cancers, and it promotes cell motility and invasion by influencing CREB signaling." (PMID 35910232, 2022). "In postoperative pancreatic cancer patients, overexpression of BCL7B accurately predicted the poor prognosis compared to the TNM staging system." (PMID 35910232, 2022). "Pancreatic cancer patients expressing high BCL7B levels had a better clinical prognosis than those expressing low BCL7B levels." (PMID 34362400, 2021). "Of note, inhibition of BCL7B in pancreatic cancer cells could dramatically reduce the invasion and motility of cancer cells by regulating CREB signaling." (PMID 34362400, 2021). "We previously reported that overexpression of PODXL, BCL7B, and ARHGEF4 in pancreatic cancer tissue is correlated with pancreatic cancer-related survival." (PMID 31166991, 2019). "It is notable that the combination of PODXL with ITGB1 and the combination of BCL7B with ITGB1 accurately predicted the postoperative outcomes of pancreatic cancer patients with or without adjuvant therapies." (PMID 31166991, 2019). "The aim of this study was to investigate the use of PODXL, BCL7B, ARHGEF4, and the integrin family member ITGB1 as useful markers for the prognosis of postoperative pancreatic cancer patients in comparison with tumor size and the tumor node metastasis (TNM) staging system." (PMID 31166991, 2019).
Williams-Beuren syndrome (3 papers, 2015 to 2023). "Deletion of BCL7B in patients with Williams-Beuren syndrome increases the risk of malignant transformation." (PMID 30908498, 2019). "Although several studies have suggested that malignant diseases occurring in patients with Williams-Beuren syndrome are associated with aberrations in BCL7B, little is known regarding the function of this gene at the cellular level." (PMID 25569233, 2015). "Although several clinical studies have suggested that malignant diseases occurring in patients with Williams-Beuren syndrome are associated with aberrations in BCL7B, little is known regarding the physiological function of this gene." (PMID 25569233, 2015). "This study may implicate a risk of malignancies with BCL7B-deficiency, such as Williams-Beuren syndrome." (PMID 25569233, 2015). "Among them, BCL7B, located on chromosome 7q11.23, is one of the deleted genes in patients with Williams-Beuren syndrome." (PMID 25569233, 2015). "BCL7B has been shown to regulate the Wnt signaling pathway, which may drive the relationship of this gene with the genetic disorder, Williams syndrome." (PMID 36801810, 2023). "BCL7B, a member of the human BCL7 gene family, is deleted in patients with Williams-Beuren syndrome." (PMID 25569233, 2015).
Burkitt lymphoma (2 papers, 2013 to 2018). A rare form of malignant mature B-cell non-Hodgkin lymphoma. "BCL7B was found to be directly involved in a three-way gene translocation together with Myc and IgH in a Burkitt lymphoma cell line, and the disruption of the N-terminal region of BCL7B was thought to be related to the pathogenesis of a subset of high-grade B cell non-Hodgkin lymphoma." (PMID 23476131, 2013).
glioblastoma (2 papers, 2022 to 2023). The most malignant astrocytic tumor (WHO grade IV). "Our results showed that BCL7B was a potential diagnostic and prognostic biomarker in multiple cancer such as glioblastoma multiforme (GBM) and oral squamous cell carcinoma (OSCC)." (PMID 35910232, 2022).
sarcoma (2 papers, 2022 to 2023). A usually aggressive malignant neoplasm of the soft tissue or bone. "Our previous study found that BCL7B was associated with immune infiltration in sarcoma, which was consistent with this study." (PMID 35910232, 2022). "Low expression of BCL7B was associated with a poor prognosis in kidney renal clear cell carcinoma (KIRC), kidney renal papillary cell carcinoma (KIRP), skin cutaneous melanoma (SKCM), thyroid carcinoma (THCA), and sarcoma (SARC)." (PMID 35910232, 2022). "BCL7B was expected to show potential as a biomarker for prognosis and immunotherapy analysis due to a correlation found between BCL7B expression and immune cell infiltration in sarcoma, and interestingly, the correlation was found to be reversed in certain cancer types." (PMID 37648998, 2023). "For example, it was reported that the low expression of BCL7B was associated with a poor prognosis in kidney renal clear cell carcinoma (KIRC), kidney renal papillary cell carcinoma (KIRP), skin cutaneous melanoma (SKCM), thyroid carcinoma (THCA), and sarcoma (SARC)." (PMID 37648998, 2023).
adrenocortical carcinoma (1 paper, 2022). "The BCL7B gene expression had varying degrees of correlation with 24 immune cell subsets in 37 tumor environments such as adrenocortical carcinoma (ACC) and bladder urothelial carcinoma (BCLA)." (PMID 35910232, 2022).
astrocytoma (1 paper, 2021). "BCL7A and BCL7B were identified as the two of the lowly expressed candidate genes associated with a small region of loss at 10q26.3 and 7q11.23 in astrocytoma, respectively." (PMID 34362400, 2021).
diabetic cardiomyopathy (1 paper, 2024). Diabetic cardiomyopathy is a disorder of the heart muscle in people with diabetes. "We constructed a diagnostic model of DCM, and OXCT1, CACNA2D2, BCL7B, EGLN3, GABARAP, and ACADSB were potential biomarkers, which may provide new insights for improving the ability of early diagnosis and treatment of diabetic cardiomyopathy." (PMID 38469146, 2024). "We found diagnostic and predictive biomarkers of type 2 DCM consisting of OXCT1, CACNA2D2, BCL7B, EGLN3, GABARAP, and ACADSB, which may reduce the difficulty of early prediction of diabetic cardiomyopathy, and lay a foundation for prospective research." (PMID 38469146, 2024).
endometrial cancer (1 paper, 2022). Primary or metastatic malignant neoplasm involving the endometrium (mucous membrane that lines the endometrial cavity). "In tumor tissues, the BCL7B protein level was the highest in testis cancer and lowest in endometrial cancer." (PMID 35910232, 2022).
esophageal adenocarcinoma (1 paper, 2022). A malignant tumor with glandular differentiation arising predominantly from Barrett mucosa in the lower third of the esophagus. "ROC curves showed that BCL7B gene had a high diagnostic value (AUC>0.8) in DLBC (AUC = 0.897), esophageal adenocarcinoma (ESAD, AUC = 0.853), HNSC (AUC = 0.840), OSCC (AUC = 0.825), OV (AUC = 0.847), PAAD (AUC = 0.980), SKCM (AUC = 0.803), GBM (AUC = 0.932), and THYM (AUC = 0.926)." (PMID 35910232, 2022).
hypertriglyceridemia (1 paper, 2022). A laboratory test result indicating elevated triglyceride concentration in the blood. "Regarding associations with hypertriglyceridemia, SNPs on the genes of BCL7B, FADS2, and TM6SF2 were found in previous studies." (PMID 36233190, 2022).
lung carcinoma (1 paper, 2021). "The positive mode has marker traits pulmonary function and the C-reactive protein, and the few markers genes (IL6R, ARHGAP10, BCL7B, PABPC4) are also involved in immune response and lung cancer progression." (PMID 34157017, 2021).
lymphoma (1 paper, 2026). A malignant (clonal) proliferation of B- lymphocytes or T- lymphocytes which involves the lymph nodes, bone marrow and/or extranodal sites. "Initially identified through chromosomal translocations in lymphomas, the BCL7 protein family, comprising the three paralogues BCL7A, BCL7B, and BCL7C, has recently emerged as a core component of mammalian SWI/SNF ATP-dependent chromatin remodeling complexes." (PMID 42305078, 2026).
Obesity (1 paper, 2017). Accumulation of substantial excess body fat. "Nevertheless, some of these SNPs (rs1260326 (GCKR), rs13233571 (BCL7B), rs2847281 (PTPN2), and rs4129267 (IL6R) predicting hsCRP and rs630014 (ABO), rs651007 (ABO), and rs687289 (ABO) predicting IL-6) were associated with obesity-related traits." (PMID 28819125, 2017).
prostatic cancer (1 paper, 2019). "Hypermethylation of RASGRF2 has been associated with recurrence of prostatic cancer; BCL7B is a member of the BCL7 gene family (along with the genes BCL7A and BCL7C), in humans, the decrease in BCL7A expression is associated with development of NHL and epithelial lymphoma." (PMID 30908498, 2019).
cancer (7 papers, 2015 to 2025). A tumor composed of atypical neoplastic, often pleomorphic cells that invade other tissues. "In this study, to characterize the function of BCL7B and thus gain a better understanding of cancer pathology, BCL7B-deficient cancer cell lines (ΔBCL7B-1, ΔBCL7B-2 and ΔBCL7B-3 cell lines) were generated with the CRISPR/Cas9 genome-editing system." (PMID 37648998, 2023). "Compared with the existing BCL7B gene-related experiments, our work systematically and comprehensively studied the functional role of BCL7B gene in pan-cancer, highlighting its prognostic and diagnostic value, and potential mechanism in cancers." (PMID 35910232, 2022). "We also explored the association between the BCL7B expression level and patient prognosis in several cancers." (PMID 35910232, 2022). "GSEA suggested that BCL7B was notably associated with cancer-related and immune-related pathways." (PMID 35910232, 2022). "BCL7B expression∗ associated with age and gender of cancer patients in pan-cancer." (PMID 35910232, 2022). "In this study, to better understand cancer pathology, we focused on the B-cell lymphoma 7 protein family member B gene (BCL7B), which is deleted in Williams-Beuren syndrome, a rare neurodevelopmental disorder." (PMID 37648998, 2023). "We thus reveal the cell characteristics of the ΔBCL7B cells and describe BCL7B function in detail, generating hints for overcoming cancer pathology." (PMID 37648998, 2023). "The regulation of BCL7B expression in cancer cells gives rise to cancer stem cell-like characteristics and the acquisition of an immune evasion phenotype." (PMID 37648998, 2023). "Considering the limited reports of BCL7B gene in different kinds of cancers, a comprehensive analysis of BCL7B gene is necessary to explore effective prognostic biomarkers and immune-related mechanisms in cancers." (PMID 35910232, 2022). "Understanding the extent and detailed landscape of BCL7B function is important for researchers that focused on the pathogenesis and development of cancers." (PMID 35910232, 2022). "Relationship between BCL7B gene expression and DNA methylation (Illumina methylation 450 data and cg27441048 probe) in pan-cancer." (PMID 35910232, 2022). "We surveyed the BCL7B on DNA methylation patterns in normal or tumor states to illustrate their potential roles in pan-cancer." (PMID 35910232, 2022). "The Kaplan–Meier method (univariate Cox regression analysis and Kaplan–Meier curve) was used to identify the cancer types whose BCL7B gene expression was related to prognosis." (PMID 35910232, 2022). "Pan-cancer methylation patterns reveal common mechanisms and new similarities of BCL7B in different cancers." (PMID 35910232, 2022). "Here, we performed a systematic analysis and provided a complete picture of BCL7B function in human cancers." (PMID 35910232, 2022). "The results showed that BCL7B expression was significantly different across immune subtypes in 10 cancer types." (PMID 35910232, 2022). "Downregulation of BCL7B in KATOIII cells induced nuclear enlargement, which is considered a hallmark of undifferentiated cells, such as cancer cells, and is associated with the grade of malignancies in neoplastic diseases." (PMID 25569233, 2015). "Although the relationship between BCL7B expression status and poor prognosis was opposite in several cancers, it was also reported that gene set enrichment analysis (GSEA) suggested that BCL7B was notably associated with immune-related pathways in both property-type cancers." (PMID 37648998, 2023). "We also analysed another cancer cell line to confirm the BCL7B functions we identified." (PMID 37648998, 2023). "The results highlight the potential mechanism of BCL7B in the progress of different cancer types." (PMID 35910232, 2022). "In particular, BCL7B was significantly related to the pathways in cancer in CESC and THYM." (PMID 35910232, 2022). "Our study illustrated the protective and carcinogenic role of BCL7B in cancer patients." (PMID 35910232, 2022).
cancer (continued). "Differential expression of BCL7B between tumor and normal tissues existed in more types of cancers." (PMID 35910232, 2022). "Follow-up animal experiment verification and further multicenter, large-sample, prospective studies are required to testify the relationship between BCL7B and patient prognosis, to explore the role of BCL7B in cancer progress and to seek more effective treatment strategies." (PMID 35910232, 2022). "Furthermore, the accumulation of cells in the G0/G1 phase observed in BCL7B-knockdown KATOIII cells is similar to the specific profile of quiescent cancer stem cells, which also accumulate in the G0/G1 phase." (PMID 25569233, 2015). "Furthermore, the mRNA expression levels of undifferentiated markers were significantly increased in both bcl-7 knockout worms and BCL7B-knockdown cells, similar to observations made in some types of malignant cancer cells." (PMID 25569233, 2015). "However, BCL7B function in the pathology of Williams–Beuren syndrome and in the course of malignant progression of cancers remains unclear." (PMID 37648998, 2023). "However, the prognosis and immunoregulatory value of BCL7B in pan-cancer patients remains unclear." (PMID 35910232, 2022). "Much less has been described in relation to BCL7B and BCL7C function in normal or cancer biology." (PMID 36801810, 2023). "In summary, our systematic analysis provided a novel insight into the BCL7B expression, prognostic significance and the relationship between BCL7B expression and immune cell infiltration, immune checkpoints, DNA methylation, DNA repair genes, TMB, and MSI in pan-cancer." (PMID 35910232, 2022).